CXCL12 (C-X-C motif chemokine ligand 12)
Diseases named in the same sentence as CXCL12 in open-access papers (continued):
Sharing a sentence is not in itself a finding about the gene and the disease.
tumor (continued). "Adipocyte-secreted factors, such as IL-6, TNF-α, and CXCL12 support tumor development and proliferation, as well as inhibit apoptosis in multiple myeloma." (PMID 32092997, 2020). "Following co-culturing of the tumor cells with CAFs, a process that has led to increased production of CXCL12, CXCR4 inhibition has reduced the formation of spheroids that were enriched with CD44+/CD24− cells." (PMID 32582148, 2020). "Deletion of Cxcl12 in endothelial cells or pharmacological blockage of Cxcr4 is known to inhibit antral tumor growth." (PMID 31963721, 2020). "The activation of CXCR4 by CXCL12 mediates tumor cell survival and proliferation and enhances primary tumor progression, angiogenesis and metastasis." (PMID 33392074, 2020). "This review summarizes the downstream cell signaling transduction of CXCL12/CXCR4/CXCR7 axis (abbreviation: CXCL12 axis) and the role of CXCL12 axis in tumor progression, growth, survival, angiogenesis, metastasis, and chemoresistance." (PMID 33363463, 2020). "Increased secretion of CXCL12 by the tumor, for example, as a result of hypoxia or treatment, stimulates the infiltration of CXCR4 expressing immune cells." (PMID 31802362, 2020). "Another mechanism by which CXCL12 contributes to tumor angiogenesis is through the upregulation of angiogenesis-associated genes, among which IL-6 is the earliest and highest upregulated gene." (PMID 33363463, 2020). "For example, CXCL12 increases the adhesion of PC- three cells to the human umbilical vein endothelial cell monolayer in a model of tumor extravasation or intravasation." (PMID 33363463, 2020). "Accumulating evidence suggests that the CXCL12/CXCR4/CXCR7 axis plays a pivotal role in tumor development, survival, angiogenesis, metastasis, and tumor microenvironment." (PMID 33363463, 2020). "It is believed that organs with high levels of CXCL12, such as lymph nodes, lungs, liver, and bones, are the first destination of metastatic tumor cells expressing CXCR4 receptors." (PMID 31802362, 2020). "CAFs can secrete ECM components (such as type I collagen or fibrin) and several soluble factors, such as growth factors (EGF, HGF, TGF-β), metalloproteinases (MMP-1, -2, -9) or chemokines (CXCL12), to promote tumor growth and metastasis." (PMID 32984031, 2020). "Fibroblast-derived CXCL12 expands the leaky tumor vasculature by recruiting endothelial precursor cells and suppressing tight junction molecules and this facilitates tumor cell intravasation." (PMID 33414786, 2020). "Overexpression of CXCL12 was positively correlated with the number of tumor infiltrating lymphocytes and the better survival rate of OSs patients." (PMID 33281116, 2020). "A recent study indicates enhanced infiltration of T lymphocytes and natural killer cells in the tumor microenvironment by blocking CXCL12." (PMID 32963527, 2020). "Experimental evidence revealed that secretion of osteoblastic CXCL12 triggers dissemination of tumor cells from the bloodstream to the target site by binding the receptor C-X-C chemokine receptor type 4 (CXCR4) located on the tumor cells." (PMID 33747899, 2020). "For example, stromal cells in secondary lymphatic tissues constitutively secrete chemokines, such as CXCL12, that facilitate homing and survival of tumor cells expressing its main receptor, CXCR4." (PMID 32370190, 2020). "Next, we evaluated the effects of matrine on CXCL12-induced cell migration activities in tumor cells." (PMID 32630806, 2020). "To date, various signaling pathways, including PGE2, CCL2, CSF-1, TGF-β, CXCL5, CXCL12, IL-1β, and IL-6, have been identified to be involved in the infiltration and activation of MDSCs in tumor microenvironment." (PMID 32824865, 2020).
tumor (continued). "CXCL12 is involved in induction tumour growth, migration and invasiveness via engagement of C-X-C chemokine receptor type 4 (CXCR4) on malignant cells and also promotes tumour angiogenesis through mediation of endothelial progenitor molecules." (PMID 32466214, 2020). "CXCL12 regulates tumor-TME interactions, thereby promoting tumor survival, proliferation, angiogenesis, and metastasis." (PMID 33363463, 2020). "Marked co-localization of CXCR4 and CXCL12 in tumor cells was also shown in immunohistochemical examination of tumor samples, they were manifested predominantly in pseudopalisading in the areas of perinecrosis and microcystic degeneration." (PMID 32456359, 2020). "The neoplastic stromal cells are of osteoblastic origin and secrete high levels of chemokines (e.g. MCP-1 (CCL2) and SDF-1 (CXCL12)) to attract the mononuclear osteoclast precursor cells to the tumour site." (PMID 31728625, 2020). "Another spiegelmer® in clinical trials is NOX-A12, an SDF-1/CXCL12 inhibitor to prevent an interaction between hematopoietic cells and bone marrow, and improving anti-tumor treatments." (PMID 32443562, 2020). "CAFs secrete various growth factors such as TGF-β, HGF, FGF and chemokine CXCL12/SDF-1 (C-X-C motif chemokine ligand 12 or Stromal cell-derived factor 1), which together promote tumour growth, EMT and invasion in cancer cells." (PMID 32824003, 2020). "We have demonstrated that CXCL12 is a key player in the migration of CXCR4 positive adult GSCs from the tumor mass toward the SVZ." (PMID 33575218, 2020). "CXCL12/CXCR4 is a well-investigated axis that is strongly involved in all stages of tumor progression in many kinds of cancer." (PMID 31991604, 2020). "The CXCL12/CXCR4 axis is also involved in enhancing angiogenesis in the tumor environment, and therefore, metastasis." (PMID 32585812, 2020). "This modification also reduces monocyte and lymphocyte chemotaxis and pro-inflammatory and tumor-supporting activities of CXCL12." (PMID 33096815, 2020). "CXCL12/CXCR4 signal pathway participates in tumor progression and metastasis and survival, except for angiogenesis." (PMID 33292246, 2020). "Tumor cells increase the CXCR4 levels and CXCL12 production, transmitting autocrine and paracrine signals, leading to enhanced tumor growth and metastasis." (PMID 33195200, 2020). "Although CXCL12 and HMGB1 are overexpressed by different tumors and are associated with tumor progression and metastasis, the functions of the CXCL12/HMGB1 heterocomplex in cancer remain to be elucidated." (PMID 33072091, 2020). "Similar failure in phagocytosis was observed in microglia suggesting that the activation of CXCL12/CXCR4 can induce tumor-supporting functions in macrophages and microglia already at an early stage of tumor development." (PMID 33096815, 2020). "CXCL12 not only induces migration but also regulates adhesion of tumor cells with laminin, fibrinogen, stromal cells, and endothelial cells by activating cell surface adhesion molecules in pancreatic, prostate, ovarian, and small cell lung cancer (SCLC) cells." (PMID 32260318, 2020). "When present, CXCL12 expression was always membrane/cytoplasmic (both in tumor and stromal/inflammatory cells), and was invariably strong in intensity, but occurring in a variable proportion of cells." (PMID 32758242, 2020). "The chemokines CCL3 and CXCL12 represent contrasting examples of induced and constitutive production by tumor and bystander cells." (PMID 32899476, 2020). "Targeting of either CXCR-4 (CXCL-12 receptor) in breast human cancer cells or CXCL-12 in ZF significantly inhibited extravasation and metastatic tumor growth at the CHT area." (PMID 32225005, 2020). "The expression levels of CXCL12 and IL7R significantly correlated with the construction of the tumor microenvironment and somatic mutations, and they are identified as potential diagnostic and therapeutic targets in the LIHC." (PMID 33344233, 2020).
tumor (continued). "In this setting, CXCL-12 secretion was found to be responsible of CAF-S1 tumor-promoting phenotype, whereas CAF-S4 seemed to be specialized in NOTCH-dependent contractile and remodeling functions." (PMID 33553157, 2020). "This reduces the chemotaxis and proliferation of tumor cells with a high expression of the CXCL12/SDF-1 chemokine." (PMID 33114763, 2020). "Upregulation of CXCR4 expression has been observed in different human cancers, and the CXCL12/CXCR4 axis is often considered a hallmark of cancer aggressiveness and correlates with tumor size, grade and recurrence, poor prognosis and low survival." (PMID 32784743, 2020). "A total of 23 (32.9%) and 49 (70.0%) tumors showed expression of CXCL12 in tumor cells and surrounding stromal/inflammatory cells." (PMID 32758242, 2020). "Mechanistically, CAF-secretion of C-X-C motif chemokine 12 (CXCL12) guides peripheral CD8+ T cell migration towards activated CAFs located in the stromal regions surrounding the tumour." (PMID 32967079, 2020). "Increased tumor cell proliferation and growth were also found to be exerted by CXCL12 and its two receptors, CXCR4 and CXCR7/ACKR3, primarily in the context of hormonal stimulation." (PMID 32582148, 2020). "In other types of cancer, the CXCL12/CXCR4 signaling plays an important role in shaping the tumor microenvironment by macrophages." (PMID 33096815, 2020). "The CXCL12/CXCR4 pair promotes tumor cell growth and the proliferation of glioblastoma cells via the ERK1/2 and AKT pathways." (PMID 31991604, 2020). "Further highlighting this theory is results that an anti-CXCL12 antibody suppressed tumor growth and/or metastasis in various tumor models." (PMID 32098047, 2020). "The acidic tumor microenvironment increases CXCL12 production, stimulates angiogenesis, tumor proliferation and chemoresistance." (PMID 33324652, 2020). "Multiple studies have shown that Cxcl12 promotes tumor angiogenesis, tumor cell proliferation and chemoresistance." (PMID 32455670, 2020). "In tumors, CXCR4/CXCR7/CXCL12 pathway is involved in the complex scenario of tumor progression, including invasion, chemotaxis, and angiogenesis." (PMID 33260925, 2020). "The CXCR4/CXCL12 axis can promote tumor metastasis by mediating cell invasion and proliferation and also enhancing tumor-associated neoangiogenesis." (PMID 33195200, 2020). "CXCR4 was frequently expressed on breast cancer cells and guided tumor cell spread to the bone, lung, and regional lymph nodes expressing high levels of its ligand CXCL12." (PMID 32943996, 2020). "The expression levels of CXCL9, CXCL10, CXCL11, CXCL12, and CXCL14 were associated with various tumor stages in HNSCC." (PMID 33489879, 2020). "We found that the methylation level of CXCL12 gene in normal tissues was lower than that in tumor tissues, indicating that the expression level of CXCL12 in normal tissues was higher than that in tumor." (PMID 33344233, 2020). "One of the common mediators of cancer immunoresistance is the CXCL12/CXCR4 pathway due to enhanced recruitment of immunosuppressive cells in the tumor microenvironment." (PMID 33281749, 2020). "The levels of SDF-1alpha/CXCL12, a chemokine that promotes BMDCs retention in the tissue, were increased in the tumor, 2 days after local irradiation." (PMID 32656079, 2020). "CXCL12, significantly upregulated in the tumor microenvironment, increases adhesion, migration, and homing of CXCR4-positive progenitor cells to ischemic tissues requiring regeneration and neovascularisation." (PMID 33260925, 2020). "CXCL12 is released by diverse cells in the tumor microenvironment and affects both adaptive and innate immunity in distinct human malignancies." (PMID 33096815, 2020).
tumor (continued). "While CXCL12 was expressed by stromal cells, it was also detected within other compartments, including tumor and endothelial cells." (PMID 32433953, 2020). "CXCL12 (also known as stromal cell-derived factor 1, SDF-1), one of the chemokine protein family, is the main regulator of cell trafficking, affecting both tumor cells and white blood cells." (PMID 33281116, 2020). "SDF-1/CXCL12 has been correlated with cancer cell invasion by recruiting macrophages to the area surrounding the tumor." (PMID 32656079, 2020). "CXCL12 also modulates the expression and function of cell surface integrins, thereby promoting tumor cell adhesion." (PMID 33363463, 2020). "CXCL12 has been reported to promote tumor progression and predict poor prognosis in multiple tumors." (PMID 32381016, 2020). "mTOR signaling and CXCL12/CXCR4 axis have been reared as a positive feedback loop to influence the tumor migration and CXCL12 secretion." (PMID 32483450, 2020). "Inhibition of CXCL12/CXCR4 axis using a CXCR4 antagonist compromised tumor growth by altering the interaction of cancer cells with osteoblast niches." (PMID 33747899, 2020). "CXCL12 is expressed by many tumor types and supports tumor survival, and, together with CCL19/21, also favors metastatic spread." (PMID 32272610, 2020). "For instance, CXCR4 is highly expressed on many types of tumor cells allowing them to hijack CXCL12-CXCR4 pathway for metastasis of tumor cells to distinct organ sites where CXCL12 is highly expressed." (PMID 33096938, 2020). "In mouse models of PDAC, the population of CAFs expressing α-SMA exhibit increased activation of Shh signaling that inhibits the production of VEGF, CXCL-12 and IL-8, which affects tumor growth, angiogenesis and immunosuppression." (PMID 33114328, 2020). "CXCR4/CXCL12 axis inhibition has been demonstrated to revert tolerogenic polarization of tumor microenvironment and to restore sensitivity to CTLA-4 and PD-1 ICIs, overall representing a novel and effective way to counteract ICIs resistance." (PMID 33123122, 2020). "One of the major biological effects modulated by the CXCL12 axis is to promote tumor cell survival and proliferation." (PMID 33363463, 2020). "This axis is of particular interest because CXCL12 was found to promote bone resorption under physiological conditions, and in parallel is a leading factor in driving tumor cell homing to the bones in a very large number of malignancies." (PMID 32582148, 2020). "Blocking the CXCR4/CXCL12 axis also inhibited tumor growth and metastasis formation in breast cancer models." (PMID 30813533, 2019). "In a number of tumor cells, cortactin activation seems to be stimulated by CXCL12, promoting lamellipodia and invadopodia formation." (PMID 30573781, 2019). "It has been reported that mast cells accumulate in gastric cancer through the engagement of the chemokine receptor CXCR4 by CXCL12 produced by tumour cells." (PMID 31035644, 2019). "In turn, activated fibroblasts released one or more soluble signals, tentatively identified as matrix metalloproteinases and the cytokine SDF-1α/CXCL12, which accelerated the rate of tumor cell aggregation and aggregate coalescence by four-fold." (PMID 31233557, 2019). "Instead of direct tumor killing, this treatment effectively suppressed CXCL12 secretion, destroyed tumor extracellular matrix, and improved infiltration of CD8+ T cells." (PMID 30937265, 2019). "CXC chemokine receptor 7 (CXCR7), a second receptor for CXCL12, has been detected in multiple types of tumor tissues." (PMID 30636642, 2019). "CAF also secrete a lot of chemokine ligands (CXCL12/SDF1, CXCL14, CCL2, and others) that promote the proliferation of cancer cells and encourage the recruitment of tumor-associated macrophages, thereby contributing to immunosuppression." (PMID 30871158, 2019).
tumor (continued). "Interactions between CXCR4 and CXCL12 stimulate tumor cell migration and invasion of basement membrane preparation by increasing the formation of cell adhesion molecules like matrix metalloproteinases." (PMID 31248118, 2019). "For example, blocking macrophage chemokines such as CXCL12, and preventing macrophages from entering tumors, or fighting for macrophages to kill tumor cells." (PMID 31781173, 2019). "In a breast cancer model, expression of CXCL12 by tumor cells increased macrophage and vessel density, contributing to the invasion ability of tumor cells." (PMID 31878087, 2019). "NOX-A12, a spiegelmer that binds and neutralizes CXCL12, was developed for interference with CXCL12 in the tumor microenvironment and for cell mobilization." (PMID 31861277, 2019). "The CXCL12 is a proinflamatory cytokine having pleiotropic effects on chemotaxis, angiogenesis, immune response and tumor metastasis." (PMID 30921390, 2019). "Collectively, our findings confirmed that Notch1 promotes GICs invasion self-renewal and tumor growth through the AKT/mTOR pathway mediated by CXCL12/CXCR4 axis and thus provide evidence of a promising target for GBM management." (PMID 31382985, 2019). "(d) Representative analysis of CXCL12-expressing (red) EpCam+ tumor cells (green) in tumor tissues of GC patients by immunofluorescence." (PMID 30808413, 2019). "CXCL12 also promotes tumor cell proliferation and survival as well as invasion and metastasis via CXCR4." (PMID 30813533, 2019). "To confirm that CXCR4:CXCL12 axis contributes to the seeding of the bone chip at the metastatic site, we repeated the tumor xenograft at the primary site and the human bone at the metastatic site experiment with the addition of AMD3100, a CXCR4 inhibitor." (PMID 31628348, 2019). "Then, CXCR4-expressing Gr-1+ myeloid cells are promoted to infiltrate to CXCL12-secreting tumor sites, and the infiltrated cells support differentiation and activation of hepatic stellate cells via the MAP kinase pathway and fibrosis in HCC." (PMID 31474975, 2019). "In conclusion, a positive feedback is established between tumour cells, TEMs, and TAMs: tumour cells recruit TEMs by expressing CXCL12, receptor to CXCR4, which is located on the TEM surface, and TAMs through CSF-1 and TGFβ." (PMID 31554160, 2019). "Fibroblasts increase vascular permeability to promote tumor intravasation via enhancing C–X–C motif chemokine ligand 12 (CXCL12) expression." (PMID 31835465, 2019). "The CXCL12/CXCR4/ACKR3 axis is not only implicated in GB, but also in extracranial tumors and is involved in tumor progression, angiogenesis, metastasis, and survival as well as contributing to immunosuppressive networks within the tumor microenvironment." (PMID 30813533, 2019). "Polarized CD163+ (M2) macrophages were also correlated with increased angiogenesis, CXCL12 expression, and tumor progression in GC." (PMID 31885581, 2019). "TGF-β and CXCL12 are key factors in the regulation of the tumor milieu, and can lead to the expression of extracellular matrix proteins such as fibrillar collagens known to be involved in invasion and metastasis." (PMID 31514477, 2019). "Taken together, these data support a model wherein GC tumors secrete chemokine CXCL12 which in turn recruits mast cells into the tumor microenvironment by CXCL12-CXCR4 interaction." (PMID 30808413, 2019). "Several chemokines (CCL2, CCL5, CXCL1, CXCL10 and CXCL12) produced by tumour and stromal cells activate their specific mast cell receptors (CCR2, CCR3, CXCR2, CXCR3 and CXCR4), which are important for TAMC localization in TME." (PMID 31035644, 2019). "The most critical impact however is probably related to cancer metastases, since the respective tumor cells apparently hijack the CXCL12-mediated homing to the bone marrow by expressing CXCR4." (PMID 31572390, 2019).